MICB (MHC class I polypeptide-related sequence B)
Description:
Widely expressed membrane-bound protein which acts as a ligand to stimulate an activating receptor KLRK1/NKG2D, expressed on the surface of essentially all human natural killer (NK), gammadelta T and CD8+ alphabeta T-cells. Up-regulated in stressed conditions, such as viral and bacterial infections or DNA damage response, serves as signal of cellular stress, and engagement of KLRK1/NKG2D by MICA triggers NK-cells resulting in a range of immune effector functions, such as cytotoxicity and cytokine production.
Synonyms: PERB11.2
Tractability: Small molecule: it has a binding pocket of medium quality. Antibody: its Gene Ontology location is reachable by antibodies, with high confidence; UniProt places it where antibodies can reach, with medium confidence; UniProt predicts a signal peptide or a membrane-spanning region; the Human Protein Atlas places it where antibodies can reach. PROTAC: ubiquitination databases record sites on it.
Gene: Protein-coding gene on chromosome 6 (31,494,881 to 31,511,124, forward strand). Ensembl gene ENSG00000204516.
Subcellular location: Cell membrane
Subcellular location (Human Protein Atlas): Golgi apparatus; Plasma membrane; Nucleoplasm
Pathways (Reactome):
Immune System: Immunoregulatory interactions between a Lymphoid and a non-Lymphoid cell
Gene Ontology:
Molecular function: natural killer cell lectin-like receptor binding
Biological process: gamma-delta T cell activation; immune response-activating cell surface receptor signaling pathway; negative regulation of defense response to virus by host; response to heat; response to oxidative stress; response to retinoic acid; immune response; negative regulation of defense response; regulation of immune response
Cellular component: cell surface; external side of plasma membrane; plasma membrane
Genetic constraint (gnomAD): Loss-of-function variants: 27 observed, 35.78 expected, observed/expected ratio (o/e) 0.75, 90% interval 0.56 to 1.04. The upper end of that interval is the gene's LOEUF score, 1.04, which puts it in group 4 of 6, group 1 being the genes least tolerant of losing a copy. Missense variants: 426 observed, 489.1 expected, observed/expected ratio (o/e) 0.87, 90% interval 0.8 to 0.94. Synonymous variants: 153 observed, 185.1 expected, observed/expected ratio (o/e) 0.83, 90% interval 0.72 to 0.94.
Homologues: Orthologues: macaque MIC1 (77% identical), mouse Mill1 (29% identical), rat Mill1 (26% identical), mouse Mill2 (26% identical), rat Micb (21% identical). Paralogues in human: MICA (70% identical), HFE (26% identical), HLA-A (26% identical), HLA-B (26% identical), HLA-E (26% identical), HLA-F (26% identical), HLA-C (25% identical), HLA-G (24% identical), MR1 (21% identical), FCGRT (20% identical), AZGP1 (19% identical), CD1A (15% identical), and 10 more.
Diseases named in the same sentence as MICB in open-access papers:
MICB is named in the same sentence as 130 diseases in open-access papers, as found by Europe PMC text mining. Sharing a sentence is not in itself a finding about the gene and the disease. The quoted sentences say what the papers report.
melanoma (25 papers, 2016 to 2025). A malignant, usually aggressive tumor composed of atypical, neoplastic melanocytes. "Our results showed that CCNB1 knockdown led to an upregulation of MICA/MICB expression in melanoma cells, and a corresponding increase in NKG2D expression in NK-92MI cells." (PMID 40430484, 2025). "Several of their findings were replicated including C4A, MICA and MICB associated with multiple cancers as well as ASIP with skin cancers (basal cell, squamous cell carcinoma and melanoma in our analysis)." (PMID 41358317, 2025). "We discovered that epigenetic modifiers, Entinostat, Decitabine, Ricolinostat and Vorinostat increased the expression of MICA/MICB on the cells in melanoma–fibroblast bicellular spheroids." (PMID 35731974, 2022). "Given the critical role of MICA and MICB in the innate immune response to melanoma, we initially used an ELISA assay to examine the amount of MICA in the medium of irradiated cells compared to the non-irradiated control." (PMID 33789714, 2021). "The strongest effect was observed for MICA expression on the melanoma cell line and for MICB on the 59M ovarian cells, which expressed the highest basal levels of their respective ligands." (PMID 30908480, 2019). "Serum CEACAM1, MICA and MICB were previously reported as poor prognostic markers in melanoma, but the relevance of pericardial involvement has never been evaluated." (PMID 26909604, 2016). "We therefore performed qRT-PCR with MICA and MICB mRNA specific primers using the melanoma cells FM79, FM82 and IF6 as positive controls." (PMID 26902929, 2016). "In this context, the expression of the NKG2DL MICB on melanoma cells induced only by guadecitabine and DAC treatment, could contribute to the immune recognition of transformed cells and accordingly, to their apoptosis." (PMID 30581389, 2018). "As a methodology, SFD is able to reveal well-known proteins in melanoma exosomes that are immune-related and are also surface-expressed proteins, such as CD26 (DPP4), CD44, CALR, B7-H3 (CD276), CSF1, ICAM1, L1CAM, MICB, APOH, TIMP1, and CD39." (PMID 40805206, 2025). "Consistent with results from GDC TGCA SKCM data base, we observe a correlation between high MICA/MICB serum levels and poor OS as well as PFS in a cohort of patients with advanced melanoma." (PMID 39837817, 2025). "This work also shows that BRAFi and MEKi, as solo or combined treatments in vitro, decreased soluble MICA, MICB and ULBP2 in supernatants from BRAF-mutant melanoma cells." (PMID 36726591, 2022). "The baseline concentration of IFNγ-inducible chemokine CXCL10 was higher in melanoma, whereas higher serum concentrations of MICA and MICB-both soluble NKG2D ligands-were detected in UC." (PMID 34071888, 2021). "Significantly, siRNA-mediated depletion of MITF blocked the radiation-induced increase in extracellular MICB, consistent with MITF knockdown preventing the shedding of NKG2D ligands in melanoma." (PMID 33789714, 2021). "Nevertheless, the treatment of melanoma cells with 1 mM VPA has been shown to induce only MICA, MICB and ULBP-2, mediated by the ERK pathway, which is also consistent with our results using Panc89 and PC-3 tumor cells." (PMID 30972064, 2019). "MICA (but not MICB) was also present in melanoma EVs isolated from plasma of melanoma patients and these EVs downregulated NKG2D in primary human NK cells, suggesting functional impairment." (PMID 36081494, 2022). "For example, the absence of soluble ULBP1 and MICB were related with better clinical outcome for melanoma patients treated with anti-CTLA-4 or anti-PD-1 antibodies." (PMID 36726591, 2022). "We implanted the murine mouse prostate tumor cell line RM9 and melanoma cell line B16F10 that were engineered to express human sMICB (designated as RM9-sMICB and B16-sMICB respectively) subcutaneously into cohorts of syngeneic MICB transgenic mice." (PMID 26625316, 2016).
melanoma (continued). "In our study, ovarian and melanoma tumour cells with a platelet cloak could be induced to release soluble NKG2DL into the tumour cell microenvironment and that NKG2D was actively suppressed using recombinant MICA and MICB proteins." (PMID 30908480, 2019). "Similar to the results from the analyses of the MCC tumor samples, MICB mRNA expression was low, but still higher than MICA mRNA, with relative expression ranging from approximately 0.02 to 0.48 when calibrated to the positive control melanoma cell line IF6’s mRNA expression." (PMID 26902929, 2016). "Also the NK activating ligand MICB was induced/up-regulated by guadecitabine and DAC treatment in 57.1% (8/14) and by AZA in 14.2% (2/14), while MICA was up-regulated (FC ≥2) by guadecitabine and DAC treatment in 14.2% (2/14) and by AZA in 7.1% (1/14) of melanoma cell lines." (PMID 30581389, 2018).
dengue (21 papers, 2013 to 2025). "Several genetic loci associated with dengue fever have been identified in various studies, including MICB rs3132468 and PLCE1 rs376552423." (PMID 37833411, 2023). "A previous genome-wide association study identified 2 susceptibility loci for severe dengue at MICB rs3132468 and PLCE1 rs3740360 and further work showed these mutations to be also associated with less severe clinical presentations." (PMID 28599625, 2017). "A MHC class I polypeptide-related sequence B (MICB) single nucleotide polymorphism (SNP) was previously associated with symptomatic dengue compared to non-dengue causes of acute febrile illnesses in infants." (PMID 24869966, 2014). "The MICB single nucleotide polymorphism (SNP) rs3132468 was also associated with symptomatic dengue compared to non-dengue causes of acute febrile illnesses in children and adults, and in infants." (PMID 24869966, 2014). "The MICB polymorphism (MICB SNP rs3132468) associated with symptomatic dengue in infants is an A/G change in an intron region of the human MICB gene (dbSNP database, NCBI)." (PMID 24869966, 2014). "The present study in Thai patients with dengue successfully replicated the associations of MICB and PLCE1 SNPs with DSS that were reported by GWAS in Vietnamese patients." (PMID 24884822, 2014). "The importance of MICB in dengue susceptibility was also indicated by GWAS with a large number of pediatric cases in Vietnam, where certain MICB and PLCE1 alleles showed a significant association with DSS." (PMID 24829565, 2014). "This strongly suggests a role for this MICB variant in susceptibility to overall clinically apparent dengue disease." (PMID 24829565, 2014). "Consistent with the findings in older children, this pooled analysis revealed a significant association between dengue in infants and MICB rs3132468 (OR = 1.48; P = 0.0075), as well as PLCE1 rs3740360." (PMID 23536857, 2013). "It is plausible that the MICB risk-associated phenotype is associated with an impaired NK cell response, potentially resulting in a higher in vivo virus titer and an increased risk of developing both symptomatic and severe dengue." (PMID 24829565, 2014). "For example, it is plausible that the MICB rs3132468 genotype is associated with an impaired NK cell response, potentially resulting in a higher in vivo virus titre and an increased risk of developing both symptomatic and severe dengue." (PMID 23536857, 2013). "Also, MICA and MICB genes have been associated with susceptibility to dengue in Cuba, partially overlapping previous results reported in the only genome-wide association study (GWAS) performed so far in Vietnamese children, and showing significant association of MICB and PLCE1 genes with DSS." (PMID 28241052, 2017). "Previous studies identified associations between MICA and MICB (MHC class I chain-related genes) within the extended major histocompatibility complex (MHC) region and hepatitis C39 and dengue virus infections, both members of the Flaviviridae family." (PMID 41377660, 2025). "Multiple HLA alleles have been identified as factors of susceptibility or protection against dengue across diverse populations, including HLA class I and II alleles and proteins like MICA, MICB, and LTA." (PMID 40006967, 2025). "Our results further showed the association between MICB rs3132468 and DSS, as well as PLCE1 rs3740360 and DHF in secondary dengue among Indonesian patients." (PMID 37958261, 2023). "We examined the associations of MICB and PLCE1 genotypes with platelet counts, as an important hematological parameter in dengue." (PMID 37958261, 2023). "Another study revealed that MICB rs3132468 and PLCE1 rs3740360 are significantly associated with clinical phenotypes of dengue less severe than DSS." (PMID 37958261, 2023). "This study investigated associations of variations in MICB (rs3132468) and PLCE1 (rs3740360, rs3765524) with dengue severity and thrombocytopenia in both the Indonesian and Taiwanese populations." (PMID 37958261, 2023).
dengue (continued). "In total, 160 dengue patients from the Indonesian population were recruited and genotyped for MICB rs3132468 and PLCE1 rs3740360, rs3765524." (PMID 37958261, 2023). "Further support for a possible role of NK cells is provided by a genome-wide association study that identified an association between a polymorphism in MICB (an NK cell–activating ligand related to KLKR1) and dengue severity." (PMID 35267010, 2022). "This study aimed to explore the functional basis of specific mutations in the MICB and PLCE1 genes previously shown to be associated with severe dengue." (PMID 28599625, 2017). "Two thousand seven hundred forty two dengue cases were successfully genotyped at MICB rs3132468 and PLCE1 rs3740360." (PMID 28599625, 2017). "Genetic variants of MICB and PLCE1 have also been found to be associated with less severe forms of dengue, and also dengue in infants." (PMID 26968374, 2016). "In the first genome-wide case–control genetic association study performed in dengue, several SNPs associated with DSS that are significant at the genome-wide level were identified, the most striking associations being SNPs in the MICB and PLCE1 genes." (PMID 26968374, 2016). "A recent study has shown that MICB and PLCE1 genes’ 3′- and 5′-UTR SNPs, which are associated with DSS, are implicated in the worsening of symptoms, from less severe symptoms of dengue to DSS, in children with dengue." (PMID 27038471, 2016). "This requires to be studied in future by the evaluation of the expression levels of MICB and the viremia titer in patients with dengue." (PMID 24884822, 2014). "This study identified association of major histocompatibility complex (MHC) class I polypeptide-related sequence B (MICB), and phospholipase C, epsilon 1 (PLCE1) with DSS, and a subsequent study extended the findings to less severe pediatric dengue fever." (PMID 24517970, 2014). "Previous association studies using cord blood controls suggest that MICB and PLCE1 SNPs are associated with not only DSS but also less severe form of dengue." (PMID 24884822, 2014). "The present study revealed that MICB and PLCE1 SNPs are associated with a progression from less severe symptom of dengue to DSS in Thai children with dengue." (PMID 24884822, 2014). "We measured circulating levels of soluble (s)MICB in the sera of infants with symptomatic primary dengue virus infections." (PMID 24869966, 2014). "Recently, genome-wide association studies have shown an association between MICB and MICA, which encode ligands of the activating NK receptor NKG2D, and dengue disease outcome." (PMID 24829565, 2014). "The aim of this study was to define the extent to which MICB (rs3132468) and PLCE1 (rs3740360) were associated with less severe clinical phenotypes of pediatric and adult dengue." (PMID 23536857, 2013). "We have shown that the MICB rs3132468 and PLCE1 rs3740360 genotypes are associated with clinically apparent dengue in both adults and children, which is a significant extension from the earlier GWAS on DSS cases alone." (PMID 23536857, 2013). "This study confirms that the MICB rs3132468 and PLCE1 rs3740360 risk genotypes are not only associated with DSS, but are also associated with less severe clinical phenotypes of dengue, as well as with dengue in infants." (PMID 23536857, 2013). "Similar findings of a previous study in Vietnam indicated that the functional basis of MICB and PLCE1 variants in thrombocytopenia of dengue patients remains unclear." (PMID 37958261, 2023). "Therefore, further studies with a larger sample size and more clinical information are needed to confirm the associations of MICB and PLCE1 variants with the severity of dengue." (PMID 37958261, 2023). "Since the majority of Indonesian patients in this study had a prior infection with another serotype of dengue virus, i.e., secondary dengue (62.5%), we investigated correlations of the MICB or PLCE1 genotypes with the severity of dengue, stratified for primary and secondary infections." (PMID 37958261, 2023).
dengue (continued). "A genome-wide association study has identified SNP rs3132468 in the MHC class I polypeptide-related sequence B (MICB) and SNP rs3765524 in the phospholipase C epsilon 1 gene (PLCE1) to be associated with DENV infection and severe dengue in a Vietnamese population." (PMID 32913345, 2020). "Although profound knowledge concerning the underlying molecular mechanisms for both dengue fever and DSS is still missing, functional polymorphism in MICB and PLCE1 genes alter the binding affinity of transcription factors in an allele-specific manner and shape susceptibility to DSS." (PMID 27038471, 2016). "However, the limitation is that the possible association of MICB and PLCE1 SNPs with susceptibility to less severe form of dengue cannot be assessed, since only patients with symptomatic dengue infection are available." (PMID 24884822, 2014). "Pooled analysis of the paediatric and adult cohorts indicated a significant association between MICB rs3132468 and dengue cases without shock (OR = 1.15; 95%CI: 1.07 – 1.24; P = 0.0012)." (PMID 23536857, 2013). "Across the 7 cohorts (4 pediatric and 3 adult) there were 297 DSS cases (161 pediatric and 136 adult), 3500 non-DSS dengue cases (2759 pediatric and 741 adult cases), and 164 cases of infants with dengue that were successfully genotyped at MICB rs3132468 and PLCE1 rs3740360." (PMID 23536857, 2013). "Pooled analysis of genotype data from the pediatric patient cohorts revealed that non-DSS dengue cases were significantly more likely to carry the MICB risk allele rs3132468 than controls (per-allele odds ratio (OR) = 1.16; 95%CI: 1.07 – 1.25)." (PMID 23536857, 2013). "Thus this study tested the hypothesis that the MICB (rs3132468) and PLCE1 (rs3740360) variants were associated with clinically important laboratory features of dengue." (PMID 28599625, 2017). "We have previously speculated that mutations in MICB might result in impaired induction of anti-viral effector functions in NK cells with the consequence being a greater DENV-infected cell mass in vivo, a recognised risk factor for severe dengue." (PMID 23536857, 2013). "The SNP associations identified at MICB (rs3132468) and PLCE1 (rs3740360) by the GWAS study were in the context of pediatric patients with DSS, leaving unanswered the question whether they are also associated with less severe clinical phenotypes of dengue." (PMID 23536857, 2013). "The association of the MICB rs3132468 genotype with clinical phenotypes of dengue less severe than DSS indicates a role for this variant in susceptibility to overall clinically apparent dengue and not just severe disease." (PMID 23536857, 2013). "MICB encodes an activating ligand for natural killer cells, and possibly CD8+ T cells, raising the possibility that mutations in this gene may result in altered antiviral effector functions and an associated increased viral burden, a recognised risk factor for the development of severe dengue." (PMID 28599625, 2017). "We also note significant association between both SNPs (OR = 1.48; P = 0.0075 for MICB rs3132468 and OR = 0.75, P = 0.041 for PLCE1 rs3740360) and dengue in infants." (PMID 23536857, 2013). "While previous work has demonstrated an association between genetic variants of MICB and PLCE1 and both severe and non-severe dengue, the functional basis of these associations is not clear." (PMID 28599625, 2017).